ENSG00000227733 (novel transcript)
Synonyms: LOC101927468
Gene: Long non-coding RNA gene on chromosome 1 (148,159,213 to 148,263,380, reverse strand). Ensembl gene ENSG00000227733.
Gene Ontology:
Molecular function: triplet codon-amino acid adaptor activity
Biological process: translation